SETD2 (SET domain containing 2, histone lysine methyltransferase)
Diseases named in the same sentence as SETD2 in open-access papers (continued):
Sharing a sentence is not in itself a finding about the gene and the disease.
tumor (continued). "Subsequent bi-allelic SETD2 loss due to mutations could further contribute to tumor progression and metastasis by impacting H3K36me3-dependent processes such as MMR (via MSH6) and possibly mRNA processing." (PMID 35661267, 2022). "These three processes may compositely underlie major tumor suppression pathways regulated by SETD2 in human cancers." (PMID 35581654, 2022). "In earlier reports, it has been shown that the loss of SETD2 resulted in a reduction of the H3K36me3 mark and accelerated tumor development, suggesting a tumor-suppressor activity associated with H3K36me3 functioning in a critical but unknown locus." (PMID 33692332, 2021). "They reported that the loss of Setd2 gene had initial tumor promoting effects." (PMID 34781949, 2021). "Interestingly, we observed a significant correlation between the frequencies of SETD2 mutation and median tumor mutation burdens across multiple tumor types (correlation coefficient, 0.62; P = 0.005)." (PMID 34127768, 2021). "We speculate the mutation of SETD2 results in the enrichment of tumor mutation-specific neo-antigens in the cell surface, the immune system will recognize and attack these cells with the help of ICIs." (PMID 34127768, 2021). "In addition, the three SETD2 variants were all novel and deleterious, further indicating its tumor suppressor function." (PMID 34895266, 2021). "The results confirmed the existence of the SETD2 mutation (p.D1890fs6*) at an AF of 74%, substantially higher than that in the undissected tissue, suggesting that its presence was limited exclusively to the tumor tissue." (PMID 32674319, 2020). "Notably, 2 paired epithelial and mesenchymal samples from one tumour presented with convergent mutations of SETD2 and NSD1, which have been described to be associated with an aggressive phenotype in ccRCC9." (PMID 31959902, 2020). "Additionally, while it did not pass our multiple testing significance threshold, we also observed a candidate association between the EPAS1 germline variant rs57579899 and SETD2 tumor mutation (p = 0.012)." (PMID 33121461, 2020). "All of these data suggest that mutation of SETD2 gene or its functional deficiency exists in tumors, and it may function as a tumor suppressor." (PMID 32231741, 2020). "Thus, given its frequency of inactivation in ccRCC, its critical role as a tumor suppressor, and its possible use as progression marker in ccRCC, effort have been placed to elucidate the biological consequences of SETD2 loss of function in ccRCC cells." (PMID 31988284, 2020). "SETD2 is lost or mutated in various cancers, supporting a tumor suppressive role of the protein." (PMID 30818762, 2019). "Interestingly, a study of ccRCC intratumoral heterogeneity identified distinct SETD2 mutations across subsections of an individual tumor, suggesting a selection bias for SETD2 mutation in the course of ccRCC development." (PMID 30774762, 2019). "This study also found somatic mutations in SETD2 in 21% of canine tumor samples." (PMID 31130627, 2019). "In people, SETD2 has predominantly been associated with a tumor suppressor function via inactivating mutation in clear cell renal cell carcinoma and hematologic malignancies, possibly through the effects of its loss on generation of genomic instability and unchecked transcriptional initiation." (PMID 31341965, 2019). "One of the leading hypotheses suggests that loss of SETD2 function in tumor cells decreases levels of H3K36me3, which subsequently leads to alterations in gene regulation, increased spontaneous mutation frequency and chromosomal instability." (PMID 30419952, 2018). "SETD2-inactivating mutations have been implicated in a number of tumor types." (PMID 30419952, 2018). "In breast cancer, SETD2 expression levels are negatively associated with increasing tumor stage." (PMID 30150556, 2018). "However, one patient (#13) had tumor recurrence and a subsequent resection which showed the same SETD2 mutation (p.I1398T) at a similar VAF." (PMID 30419952, 2018).
tumor (continued). "It is interesting that PBRM1, BAP1, and SETD2 are all located at chromosome 3p, close to the 3p25 locus, indicating that these tumor suppressors might be functionally linked." (PMID 28846693, 2017). "In the same tumor, distinct mutations at different parts of the tumor could inactivate the same tumor suppressor genes such as SETD2, Phosphatase And Tensin Homolog (PTEN), and Lysine Demthylase 5C (KDM5C/JARID1C)." (PMID 28445125, 2017). "Interestingly, BAP1 mutations in 15% of all ccRCC have been reported together with SETD2 mutations being more frequent in higher stage tumours and associated with worse prognosis." (PMID 28486536, 2017). "Sanger sequencing validated that all of the SETD2 mutations were present in tumour DNA." (PMID 27282254, 2016). "Additionally, mutations of KDM5C and SETD2 were significantly associated with tumor size (p = 0.019 and p = 0.0445)." (PMID 26848523, 2016). "Furthermore, the occurrence of SETD2 (3p21) mutation was significantly higher in the NF2 loss than in the remaining uRCC tumours (44% versus 9%, Fisher's exact test, P=0.004)." (PMID 27713405, 2016). "Among various genes coding for enzymes with methytransferase activity, SETD2 shows a very high frequency of somatic mutations in various cancer types, with high incidence of deleterious and loss-of-function mutations supporting its tumour suppressor function." (PMID 27600764, 2016). "Notably, the fact that three tumours with a monoallelic SETD2 mutation showed a strong reduction in H3K36me3 level suggests molecular alterations with a dominant phenotype." (PMID 27600764, 2016). "Importantly, Setd2 is one of the most frequently mutated genes among chromatin regulators in various tumor types." (PMID 25925577, 2015). "Also, a recent study showed that BAP1 and SETD2 mutations tend to appear late in tumor development, a finding that supports our observation." (PMID 25826081, 2015). "It is presently unclear exactly how SETD2 functions as a tumor suppressor, but loss of function may result in an impaired chromatin template for processes such as transcription and DNA repair." (PMID 25773741, 2015). "Upon AZD1775 treatment, all seven tumors generated from SETD2-deficient A498 cells regressed from day 3 onward, resulting in a 5.8-fold reduction in tumor size compared to vehicle-treated control animals (tumor size at day 12 = 50.2 ± 4.7 mm3 versus 291.2 ± 40.0 mm3, p < 0.0001)." (PMID 26602815, 2015). "Similarly, PBRM1 downregulation correlated with advanced tumor stage, low differentiation grade and worse patient outcome while SETD2 mutations correlated with a high relapse rate." (PMID 28326264, 2015). "It will be interesting to determine whether mutation of ZMYND11 or SETD2 occurs in these tumor types and if knockdown of these factors in the appropriate cell types recapitulates features of the diseases." (PMID 25773741, 2015). "Our present findings suggest that impaired DDR proficiency constitutes a hallmark of SETD2 mutant cancers and could reveal a novel mechanism through which SETD2 suppresses tumor development and growth." (PMID 24843002, 2014). "Our findings endorse the classification of SETD2 as a tumor suppressor and place inactivating mutations in this histone modifier at the peak of a harmful cascade of events that may ultimately drive malignant cell transformation and tumor development." (PMID 24843002, 2014). "Furthermore, SETD2 is located on the short arm of chromosome 3 and this region has been associated with permanent growth arrest of the tumour cells." (PMID 19698110, 2009). "In addition, SETD2 mutations tend to remodel tumor microenvironment and facilitate immune evasion." (PMID 41198622, 2025).
tumor (continued). "However, despite this understanding, SETD2-mutated ccRCC’s behavior in the actual tumor environment remains unclear." (PMID 39119581, 2024). "Thus, we speculated that the TME, especially the immune TME, might contribute to the SETD2‐deficient tumor progression in vivo." (PMID 36453584, 2023). "Finally, we demonstrate not only that signaling through OXPHOS and mTORC1 is required for the proliferative benefit bestowed upon tumor cells following SETD2 inactivation, but that they also represent readily actionable therapeutic vulnerabilities for patients with SETD2-deficient tumors." (PMID 36899051, 2023). "Therefore, as the majority of cancer patients carry heterozygous SETD2 mutations, SETD2 might act as a haplo-insufficient tumor suppressor." (PMID 29777171, 2018). "Therefore, our mechanistic study here might provide important insights into how those mutations disrupt Setd2 tumor suppressor functions." (PMID 25925577, 2015). "Besides VHL, other genetic alterations in subgroup-5 involve the mutation of the chromatin remodeling gene PBRM1, the mutation of the histone methyltransferase gene SETD2, which has been identified as a tumor suppressor in KIRC and high methylation rate of GSTP1." (PMID 26148869, 2015). "Among the three genes, the loss of SETD2 is typically a subclonal event, whereas the loss of PBRM1 or BAP1 usually occurs as a clonal event earlier in tumor progression." (PMID 41602827, 2026). "Although there has been increased interest in studying SETD2 in ccRCC over the past few years, research on SETD2 and its role in influencing the tumor immune microenvironment of this cancer has barely begun." (PMID 41602827, 2026). "Through next-generation sequencing (NGS) analysis of circulating tumor DNA (ctDNA) and tumor tissue DNA (ttDNA) from these patients, mutations in PBRM1, SETD2, and ROS1 were frequently detected in both ctDNA and ttDNA of non-responders." (PMID 41602395, 2026). "For example, the SETD2 gene (along with other important tumor suppressors) is located within chromosome 3p, a genomic region that is reported to show loss of heterozygosity in ~90–95% of ccRCC tumors." (PMID 40462961, 2025). "The level of SETD2 mRNA is shown to be significantly lower in oncogenic tissues and it further decreases with increasing tumor stage." (PMID 39591760, 2025). "Chromatin remodeling gene mutations were identified in 9 of 17 tumors (53%), involving BAP1 mutations in 6 tumors (35%), SETD2 mutations in 4 tumors (24%), and an ARID1A mutation in 1 tumor (6%)." (PMID 40940841, 2025). "In ccRCC models, biallelic SETD2 inactivation produces replication stress, elevated DNA damage in vivo, and a pattern of branched tumor evolution, implicating SETD2 in preserving chromosomal integrity across the S phase." (PMID 41440218, 2025). "Recurrent SETD2-inactivating mutations and altered H3K36me3 levels are found in cancer at high frequency and numerous studies indicate that SETD2 acts as a tumor suppressor." (PMID 39591760, 2025). "Other gene mutations are also involved in the formation of RCC: PBRM1 is potentially associated with tumor immune escape; BAP1 and SETD2 participate in DNA repair regulation; and MTOR regulates the critical PI3K/AKT/mTOR signaling pathway." (PMID 41405787, 2025). "The SETD2 gene is located on chromosome 3, p21.31 2, and is widely recognized for its tumor-suppressive functions." (PMID 40959108, 2025). "Murine studies (including our work) establish Setd2 as a critical tumor suppressor in hematopoiesis." (PMID 41198622, 2025). "Stabilization of SETD2 also leads to increased cell proliferation, although it is considered a tumour suppressor." (PMID 39591760, 2025).
tumor (continued). "Co-mutation of SETD2 and ATRX occurs in up to 18% of paediatric HGG and, as such, this finding sheds light on the genetic aetiology of these highly aggressive tumours." (PMID 39921567, 2025). "For subgroup analysis by genetic mutations, the CDX model with BAP1 mutations exhibited the most rapid tumor growth rate, compared with the models with VHL, PBRM1, and SETD2 mutations (P < 0.01)." (PMID 40856833, 2025). "In vivo, SETD2 ablation accelerates lethality in an autochthonous KRASG12C-driven LUAD mouse tumor model." (PMID 40462961, 2025). "Histone methyltransferase SET domain containing protein 2 (SETD2), the key enzyme catalyzing this modification, has been identified as a tumor suppressor and immune modulator." (PMID 40786181, 2025). "It was noted that SETD2 is located at 3p21.31, which commonly shows copy number variant (CNV) loss in a range of tumours." (PMID 39921567, 2025). "These lipid-laden CAFs, in turn, supply lipids to Setd2-deficient tumor cells, thereby supporting mitochondrial oxidative phosphorylation (OXPHOS) and promoting tumor growth." (PMID 40948749, 2025). "According to the latest research, variations in the VHL, PBRM1, and SETD2 genes are the strongest evidence for tumor growth and how it responds to therapy." (PMID 41479787, 2025). "The abnormally elevated LEDGF leads to the accumulation of purine nucleotides in SETD2‐mutant ccRCC, thereby satisfying the requirements for the extensive proliferation of malignant tumor cells." (PMID 40548925, 2025). "For example, in terms of immune regulation, SETD2’s regulation of regulatory T cells (Tregs) affects tumor control and antiviral response." (PMID 40786181, 2025). "The patient's tumor demonstrated mutations in VHL, PBRM1, and SETD2, which are commonly associated with clear cell RCC and have significant implications for tumor behavior and therapy selection." (PMID 40600205, 2025). "Most patients with RCC have a deletion of chromosome 3p and genomic alterations in the Von Hippel–Lindau (VHL) tumor suppressor allele, accompanied by the subsequent loss of other tumor suppressor genes, including PBRM1, SETD2, BAP1, and/or KDM5C." (PMID 41440218, 2025). "Although CNV loss does not always correlate with decreased gene expression, a study demonstrated that SETD2 was one of 81 tumour suppressor genes in which decreased gene expression appeared to be induced by CNV loss." (PMID 39921567, 2025). "The downregulation of SETD2 is closely associated with prostate cancer development, which reinforces the idea of SETD2 exerting a biological function as a tumor suppressor." (PMID 40959108, 2025). "Mutations in PBRM1 and SETD2 often co-exist while mutations in PBRM1 and BAP1 seem mutually exclusive at the clone level, with distinct tumor phenotypes." (PMID 37999735, 2024). "Through transforming growth factor (TGF)-β1 signaling, mutated SETD2 tumor cells were found to activate HGG-associated microglia in IDH-WT GBM, which promoted tumor progression." (PMID 39765675, 2024). "To further verify the underlying impact of losing SETD2 expression, we used A375SETD2ko and A375WT, respectively, to construct nude mice tumor model and measured the tumor volume after cells were implanted for 26 days." (PMID 38843391, 2024). "Recently, it has been shown that multiple subclonal drivers including PBRM1, SETD2, or BAP1 mutations contribute to high genetic intra-tumor diversity in ccRCC and impact on clinical outcomes." (PMID 37999735, 2024). "Both shared common features, such as the hypermethylation of functional regions in the genome, enrichment for somatic driver mutations (SETD2 and PBRM1), and associations with tumour stage, grade, and overall survival." (PMID 39592856, 2024).
tumor (continued). "Among the evaluated genes, SETD2 was a promising candidate, due to the known tumour suppressive role of the SETD2 methyltransferase, lost or mutated in various cancers, and its importance for DNA replication, DNA repair and genome instability." (PMID 39580568, 2024). "SETD2 (SET Domain-Containing Protein 2), a histone methyltransferase involved in chromatin remodeling and gene regulation, has recently emerged as a tumor suppressor." (PMID 38843391, 2024). "SETD2 has been attracting a lot of interest in recent years due to its involvement in tumor initiation and progression." (PMID 38611113, 2024). "Epigenetic regulators like CREBBP and SETD2 control gene expression through histone modifications, with their dysregulation leading to tumor development." (PMID 39273340, 2024). "To test this, we analyzed genomes from a diversity of tumor types with driver mutations in either ATM, MEN1, SETD2, BRCA1, BRCA2 and ATRX." (PMID 38909016, 2024). "The results showed that SETD2 expression was upregulated in human HCC tumor tissues and in 6 HCC cell lines compared with that in impaired adjacent peritumoral tissues and normal liver cell lines, respectively." (PMID 39668826, 2024). "Alterations in BAP1, PBRM1, and SETD2 are common and important co‐driving factors in tumor development." (PMID 39166457, 2024). "Pathways linked to melanogenesis were enriched in SETD2 low expression CM samples and SETD2 ko A375 tumor tissue harbored by nude mice." (PMID 38843391, 2024). "These tumours have alterations in chromosomal numbers and are associated with mutations in MET, CDKN2A, SETD2, BAP1, PBRM1, NFE2L2, and mTOR genes and have a better prognosis when compared with clear cell RCC in the organ-confined stage." (PMID 38265103, 2024). "The data indicated that SETD2 was upregulated in LIHC tumor tissue compared with normal tissue (P < 0.001)." (PMID 39668826, 2024). "As a key component of common tumor suppressor mechanisms, SETD2-H3K36me3is an important target for clinical disease diagnosis and treatment." (PMID 37359376, 2023). "CcRCC also displayed markedly elevated methylation-level entropy, which was significantly higher in SETD2 wt tumors and correlated with markers of tumor aggressiveness." (PMID 37120552, 2023). "Already in 2013, the genome of the clear cell RCC was identified, which is characterized by the absence or mutation of the VHL tumour suppressor gene (localized at 3p25) and frequent inactivation of the chromatin-modifying genes PBRM1, BAP1 and SETD2." (PMID 36672289, 2023). "In the SETD2-knockdown tumor model, increased CD8+ T cell infiltration and fewer MDSC following combined treatment with DAC and anti-PD-L1." (PMID 37025591, 2023). "In parallel, each region was scored by H&E pathologic analysis of key tumor features such as grade, stage, and necrosis, and IHC was used to assess levels of H3K36me3 (the mark written by the SETD2 histone methyltransferase), and DNA methylation (5mC)." (PMID 37120552, 2023). "A recently accepted notion of RCC progression is that VHL mutation function as an initial event to drive tumorigenesis, while PBRM1, BAP1 and SETD2 subsequent trigger defects in DNA repair system and abnormal tumor growth." (PMID 37064095, 2023). "In the present study, we showed that SETD2 plays a critical role in ccRCC progression and prognosis as well as impacts tumor cell sensitivity to erastin." (PMID 37604811, 2023). "Low SETD2 expression was significantly correlated with clinicopathological parameters such as tumor size, TNM stage, and lymph node metastasis." (PMID 37359376, 2023). "SETD2, known as an epigenetic tumor suppressor responsible for H3K36me3 modification, plays an important role in transcriptional regulation, DNA damage repair, and other cellular processes and is reported to be altered in a range of solid cancers." (PMID 35833755, 2023).